IL6 (interleukin 6)
Diseases named in the same sentence as IL6 in open-access papers (continued):
Sharing a sentence is not in itself a finding about the gene and the disease.
Obesity (continued). "Evidence suggests that chronic inflammation and enhanced pro-inflammatory cytokine levels in the bloodstream and tissues, like TNFα and IL6, are linked to obesity." (PMID 39019936, 2024). "IR can instigate an upsurge of inflammatory cytokines associated with obesity, including IL-1β, IL-2, IL-4, IL-5, IL-6, IL-8, tumor necrosis factor-α, and interferon, which have been robustly linked to the development of PAH." (PMID 38702735, 2024). "Here, M1 macrophages can produce cytokines such as TNF‐α and IL‐6 to promote progression of obesity‐associated diseases." (PMID 38405061, 2024). "Chronic low-grade inflammation, characterized by elevated levels of pro-inflammatory cytokines such as TNF-α, IL-6, and IL-1β, is a hallmark of obesity and insulin resistance." (PMID 38920999, 2024). "The current study shows that first trimester low plasma ferritin levels (as a proxy for low iron status), low hCG, high CRP, high IL-6 levels, higher age and obesity (BMI >30) were independently associated with IH." (PMID 38330593, 2024). "Chronic ER stress, such as obesity, causes persistent inflammation in adipocytes and macrophages and induces the increased expression of the proinflammatory cytokines interleukin-6 (IL-6) and tumor necrosis factor alpha (TNFα)." (PMID 38732214, 2024). "In examining inflammatory cytokines and comorbid states, hypertension and obesity in particular were associated with an increase in pro-inflammatory cytokines, such as interleukin 6 (IL6) and interleukin 17 (IL17)." (PMID 39337456, 2024). "The Th17/Treg ratio has a major contribution to the chronic inflammation associated with obesity and can be influenced by IL6, which triggers the Th17 subset." (PMID 39518420, 2024). "Interleukin gene variation, particularly the IL-6 rs1800795 variant, is modestly associated with obesity risk." (PMID 39769263, 2024). "One of the mediators of the inflammatory response, interleukin-6 (IL-6), is strongly associated with inflammation, which is present in both obesity and type 2 diabetes (T2D)." (PMID 38250713, 2024). "The distinct behaviors of IL-10 and IL-6 in relation to obesity underline the necessity of considering individual cytokine profiles when evaluating inflammation and obesity interventions." (PMID 39180618, 2024). "Nevertheless, the connection between IL-6 trans-signaling and obesity-linked ventricular arrhythmias remains unexplored." (PMID 39125976, 2024). "Elevated IL-6 levels in obesity are linked to T2DM development, underscoring IL-6’s role in metabolic dysregulation." (PMID 39857603, 2024). "Acute infection, chronic inflammatory disease, obesity, and physiological stress cause the production of IL-6." (PMID 38645491, 2024). "Epicardial adipose tissue (EAT) is a rich local source of IL-6 signaling in obesity and a key contributor to a higher risk of cardiac events in patients." (PMID 39125976, 2024). "Obesity is associated with an inflammatory status characterized by high concentrations of inflammatory cytokines such as IL-6 and TNF-α, which can affect bone and muscle tissues." (PMID 39902393, 2024). "We found increased levels of CCL5 in patients with obesity and obesity-associated T2D, with also higher levels of IL-6 and the ratio IL-18/IL-18BP." (PMID 38315242, 2024). "Composite genotype and haplotype analyses involving all three IL6 promoter variants were linked to type 2 diabetes, obesity, and metabolic syndrome in Caucasians." (PMID 38388670, 2024). "It suppresses the production of pro-inflammatory cytokines, such as TNF-α and IL-6, thereby mitigating chronic low-grade inflammation associated with obesity." (PMID 38255203, 2024). "The aim of the study was to analyse the circulating miRNA 423-5p and miRNA 128-1 levels and their association with cytokines (TNF-α and IL-6) before intervention with adults with obesity and lean adults of the 18–23 age group." (PMID 38541185, 2024).
Obesity (continued). "Obesity is associated with systemic low-grade inflammation with elevated levels of pro-inflammatory cytokines such as IL-6 and TNF-α." (PMID 39902293, 2024). "In the current study, we investigated the genetic association of IL-6, which is a pro-inflammatory marker, in pregnant women with either pre-pregnancy obesity or type 2 diabetes and in preeclampsia cases." (PMID 38893732, 2024). "In an interdependent way, diabetes mellitus and obesity cause a chronic pro-inflammatory state with increased production of circulating pro-inflammatory cytokines (interleukin-6, tumor necrosis factor-alfa, etc.)and reactive oxygen species (ROS)." (PMID 38786968, 2024). "Animal studies have pointed out that IL-6 overexpression was able to reduce weight gain while IL-6 deficient mice developed obesity at maturity." (PMID 39683624, 2024). "Other IL-6 gene polymorphisms, such as rs1800795(G/C) and rs1800796(G/C), are the risk factors for obesity and are considered potential new targets for drug inventions in obesity treatment." (PMID 38397196, 2024). "Two studies on grade II-III obesity patients that underwent LAGB showed that rs1800795 polymorphism of IL-6 provides the opportunity to predict therapeutic response." (PMID 39125390, 2024). "Our study concentrated on some of the most vital obesity stress markers, such as leptin and IL-6, which represent crucial facets of the intricate obesity-associated stress network." (PMID 38178093, 2024). "The pro-inflammatory state in individuals with obesity is characterized by increased levels of IL-1β, Interleukin 6 (IL-6), and TNF-α, which have been implicated in the pathophysiology of OA." (PMID 39451348, 2024). "SM was also demonstrated to have inhibitory effects on obesity-induced growth and ROS production associated with decreased production of proinflammatory IL-6 and IL-1β in HepG2 cells exposed to sera from obese individuals." (PMID 38247522, 2024). "To evaluate the initial stages of the damage caused by obesity, we studied the pro-inflammatory cytokine IL-6, MDA, and endogenous antioxidants GSH and catalase-specific activity in the brain." (PMID 38182767, 2024). "Hyperglycemia induces IL-6 from macrophages and endothelium.Obesity is another risk factor seen in MetS." (PMID 39070321, 2024). "Serum zonulin levels have also been found to be increased in the context of increased intestinal permeability and are associated with insulin resistance and obesity, possibly mediated by an increase in IL-6 production." (PMID 39590844, 2024). "It is known that obesity favors the release of pro-inflammatory cytokines such as tumor necrosis factor α and Interleukin-6, which are linked to the development of inflammation, and the onset of cancer." (PMID 38398110, 2024). "On the other hand, elevated levels of IL-6 are typically associated with chronic inflammatory conditions, such as obesity and metabolic syndrome." (PMID 38933362, 2024). "The association of increased adipose tissue IL-6 production with metabolic syndrome, increased blood glucose and insulin resistance has been confirmed in human and in various animal models of obesity." (PMID 38474057, 2024). "Finding increased levels of leptin and IL-6 in ADS in association with BMI-defined obesity supports a direct BMI effect on peritumor AT." (PMID 39408921, 2024). "Skeletal muscle is the target of obesity-induced inflammation, while the obesity-induced inflammation and IR can also cause the release of specific skeletal muscle cytokines, such as IL-6, irisin, myostatin, and muscle growth inhibitor." (PMID 39474255, 2024). "During pregnancy, elevated levels of circulating cytokines (TNF-a and IL-6) are thought to drive obesity-associated metabolic inflammation." (PMID 38145995, 2024). "The review aims to analyze existing studies from 1998 to 2023 to identify potential genetic determinants that contribute to overweight and obesity risk, with a particular focus on the IL-6 rs1800795 variant." (PMID 39769263, 2024).
Obesity (continued). "The focus on IL-6 in this review arises from its pleiotropic nature and unclear effect on obesity risk." (PMID 39769263, 2024). "TNFα, IL-1β, IL-6, or IL-8 are proinflammatory cytokines that are considered obesity-linked inflammatory cytokines, predominantly in the abdominal fatty tissue." (PMID 39057082, 2024). "Distinct behaviors of IL-10 and IL-6 in relation to obesity underline the necessity of considering individual cytokine profiles when evaluating bariatric surgery outcomes." (PMID 39180618, 2024). "Obesity is also associated with the secretion of pro-inflammatory cytokines, such as interleukin-6 (IL-6) and tumor necrosis factor alpha (TNFα), as well as adipokines like leptin." (PMID 39767718, 2024). "Macrophages secrete multiple factors, such as osteopontin, IL-1β, and IL-6, which have been implicated in enhancing adipose tissue fibrosis, although less is known about the impact of obesity on macrophage function within tumors." (PMID 37296891, 2023). "Decreased insulin sensitivity correlates with immune modifications during pregnancy, such as increased circulating TNF-alpha and IL-6, which are believed to trigger obesity-associated metabolic inflammation." (PMID 37515062, 2023). "Circulating levels of IL-6 positively correlate with obesity in humans and predict the risk of insulin resistance and type 2 diabetes." (PMID 37509065, 2023). "For instance, leptin and adiponectin contribute to body weight regulation, while TNF-α, IL-6, and IL-1β are associated with local inflammation resulting from obesity." (PMID 37408757, 2023). "Obesity, another risk factor for pancreatic cancer, can induce inflammation by promoting the release of IL-6, CCL2, and CCL5, and the infiltration of macrophages and immunosuppressive cells." (PMID 36899319, 2023). "Obesity is associated with high levels of inflammation which can be measured through interleukin-6 (IL-6) and C-reactive protein (CRP)." (PMID 37566728, 2023). "Interleukin-6 (IL6) is pro-inflammatory mediator which is suggested as cause of systemic low grade inflammation in obesity." (PMID 36928463, 2023). "More research had proven that SUA had a tremendous correlation with inflammatory markers such as C-reactive protein and interleukin-6, which was extra intently associated with metabolic ailments (such as obesity)." (PMID 37547098, 2023). "These parameters were associated with MASLD components such as hyperlipidemia and obesity and correlated with insulin resistance, oxidative indicators, and inflammatory IL-6." (PMID 37998747, 2023). "Production of pro-inflammatory cytokines, including IL-1β and IL-6, has been linked to obesity’s pro-inflammatory response." (PMID 37175603, 2023). "IL-6 is another cytokine that can be produced by adipocytes and is crucially implicated in the pathogenesis of obesity and insulin resistance." (PMID 37509065, 2023). "Higher serum IL-6 levels are associated with decreased glucose tolerance, diabetes mellitus, high blood pressure, and obesity in humans." (PMID 37175603, 2023). "Consistent with this, others have shown that obesity-related systemic inflammation is associated with increased systemic as well as cerebral IL-6 levels, either by local production in the brain and/or by crossing of the blood-brain barrier from the periphery." (PMID 37457817, 2023). "Circulating endotoxins have been associated with increments of cytokines such as TNF-α and IL-6 in adipocytes and, accordingly, subclinal levels of LPS, have been linked with high-fat diets, obesity, and other metabolic disorders." (PMID 36786619, 2023). "Our data corroborated a previous study describing an inverse relationship between IL-6 and adiponectin levels in patients with obesity before and after diet-induced weight loss, which was probably related to IL-6’s inhibition of adiponectin mRNA expression." (PMID 37432255, 2023).
Obesity (continued). "Some clinical studies explore positive associations between different measures of obesity and plasma cytokines, particularly IL-6 levels, finding that one-third of the total circulating concentrations of this cytokine is derived from adipose tissue." (PMID 36935429, 2023). "In individuals with obesity, inflammatory markers such as IL-6, CRP, and TNF-α have been associated with the progression of discogenic back pain." (PMID 37959372, 2023). "It should be remembered that IGF-1 belongs to obesity-associated adipokines, proteins that along with leptin, insulin and IL-6 are also produced by adipocytes." (PMID 36835075, 2023). "This is consistent with a study demonstrating association between obesity and fatigue while controlling for other potential contributors including IL-6 levels." (PMID 36995412, 2023). "Regarding the IL6 (rs1800795) polymorphism, some studies suggest that the obesity risk allele is the G, while others suggest that it is the C." (PMID 36986146, 2023). "A recent study showed that IL-6 was required for obesity-associated Th17 cell expansion during induction of EAE with myelin oligodendrocyte glycoprotein 35–55." (PMID 36982669, 2023). "Obesity results in a low-grade chronic systemic inflammation associated with increases in two inflammatory mediators, IL-6 and TNF-α." (PMID 36986146, 2023). "As an element of IRS activation, IL-6 has been linked with many diseases, including obesity and schizophrenia." (PMID 37370004, 2023). "In past, IL-6 was associated with self-esteem, however this association in subjects with obesity and metabolic abnormalities hereby is novel." (PMID 37529617, 2023). "The inflammation caused by insulin resistance can be identified by the increasing level of the serums TNF-α, IL-2, and IL-6 in the M group, indicating the inflammatory response is caused by obesity." (PMID 37569125, 2023). "Increased circulating IL-6 and other pro-inflammatory mediators is associated with obesity during pregnancy in rodents and humans, though the extent of elevation compared to lean women likely fluctuates over the course of pregnancy and postpartum." (PMID 36984895, 2023). "Adolescents who had infections were excluded from this study, so the increase in CD4 and IL-6 levels seems to be associated with obesity." (PMID 37859769, 2023). "Obesity is linked to hyperactive adipose tissue with an inflammatory secretory phenotype including leptin and IL-6 that cause, when prolonged, subacute chronic inflammation and insulin resistance." (PMID 36768831, 2023). "Pro-inflammatory cytokines associated with obesity, such as interleukin-6 (IL-6), play a critical role in the relationship between asthma severity, lung function, and metabolic syndrome." (PMID 38292857, 2023). "The activation of IL-6/JAK/STAT3 signaling in the liver promotes the development of obesity-associated HCC through exacerbating metabolic stress-induced inflammation and immune response." (PMID 37361533, 2023). "IL-1β, IL-6, and TNF-α are classical pro-inflammatory cytokines associated aging and obesity, the levels of IL-1β, IL-6, and TNF-α in serum were significantly decreased in the Y-ASC transplantation group when compared to the old control group." (PMID 37533129, 2023). "Another inflammatory cytokine, interleukin-6 (IL-6), is also found in adipose tissue and is often implicated in obesity-related processes." (PMID 37927615, 2023). "The adipose tissue is another important source of IL-6, the latter being associated with obesity and diabetes." (PMID 37629496, 2023). "Obesity is linked to a higher grade of systemic inflammation; adipocytes are involved in the production of IL-6, which contributes to the differentiation of T lymphocytes into the Th17 subtype." (PMID 37239484, 2023). "The state of chronic inflammation associated with obesity is related to high levels of inflammatory cytokines such as IL-6, C-reactive protein (CRP), and TNF-α." (PMID 36909335, 2023).
Obesity (continued). "As a risk factor, obesity predisposes to a pro-inflammatory state through an increase in inflammatory mediators such as IL-6, TNF-α or HGBM-1." (PMID 36596839, 2023). "Some of those studies show that IL-6 deficiency led to development of obesity, liver inflammation and insulin resistance even during low-fat feeding." (PMID 36994095, 2023). "On the other hand, IL-6 produced by macrophages in obesity and aging causes an increase in lipolysis and high levels of free fatty acids." (PMID 38069224, 2023). "For example, IL-6 levels of patients with obesity were negatively associated with CD16 expression on CD11b+ HD neutrophils (rho = −0.80, p = 0.01)." (PMID 37626613, 2023). "Increased levels of circulating LBP have been determined in obesity and the metabolic syndrome and associated with increased circulating IL-6 levels, impaired insulin resistance and cardiovascular risk." (PMID 37841878, 2023). "Higher n-6 and n-6/n-3 (example: Western diets, n-6/n-3 10–16:1) are associated with obesity via increased white adipose tissue, chronic inflammation and synthesis of proinflammatory cytokine interleukin 6 (IL-6)." (PMID 36675096, 2023). "In fact, in adipose tissue, the M1 macrophages secrete high levels of pro-inflammatory cytokines (TNF-α, IL-6 and IL-1β), inducing an inflammation state and an impairment of insulin sensitivity, typically associated with obesity." (PMID 37447161, 2023). "Secondly, since obesity causes a low-grade inflammatory state, a higher production of IL-6, adiponectin, leptin, or TNF-α is present." (PMID 38068717, 2023). "Interleukin-6 (IL-6) and other pro-inflammatory cytokines can activate the hypothalamus-pituitary axis, which has been linked to hypertension, obesity, and insulin resistance." (PMID 36995575, 2023). "Obesity is associated with higher plasma levels of interleukin-6 (IL-6), C-reactive protein (CRP), and lipopolysaccharide (LPS), and accordingly, driving mononuclear cells into a pro-inflammatory (M1) state." (PMID 37238973, 2023). "Obesity is associated with low-grade inflammation, characterized by the release of pro-inflammatory cytokines including TNFα, IL-1β, and IL-6." (PMID 37373472, 2023). "IL-6, as a multifaceted cytokine, has been shown to be elevated in chronic inflammatory states such as aging, cancer, obesity and plays a role in underlying pathology of worsening disease states." (PMID 37213604, 2023). "Markers of systemic low-grade inflammation such as IL-6 and hsCRP are often elevated in obesity and T2D and associated with an increased risk of CVD." (PMID 37592243, 2023). "During pregnancy, obesity is associated with increased levels of pro-inflammatory cytokines such as IL-6 in the placenta." (PMID 37111410, 2023). "Obesity predisposes individuals to a proinflammatory state via the increased secretion of inflammatory mediators, particularly IL-6, MCP-1, and TNF-α, from adipose tissue." (PMID 36717684, 2023). "In obesity, fatty acids are elevated, which in turn activate the expression of NF-κB-associated genes/cytokines such as IL-6." (PMID 37887430, 2023). "Leptin levels were associated with IL-6 in a study investigating the relationship of these adipocytokines with overweight and obesity in participants at different ages." (PMID 37242271, 2023). "Strong evidence has underlined that obesity is characterized by increased blood proinflammatory cytokines (such as IL-1, IL-6, TNF-alpha) and oxidative stress activity." (PMID 37511687, 2023). "Obesity is often associated with low grade inflammation and elevated levels of various pro-inflammatory factors, including TNFα, IL-6, IL-1β and MCP-16." (PMID 37386070, 2023). "While different to an acute inflammatory episode, obesity is known to be associated with a prolonged increase in circulating pro-inflammatory cytokines, including IL-6." (PMID 36984895, 2023). "Obesity before pregnancy is linked to high levels of pro-inflammatory cytokines in the placenta and circulating IL-6 throughout pregnancy." (PMID 37229273, 2023).